INS (insulin)
Diseases named in the same sentence as INS in open-access papers (continued):
Sharing a sentence is not in itself a finding about the gene and the disease.
Obesity (continued). "Interestingly, in obesity the CSF/plasma insulin ratio is decreased, a finding that should be taken within broader context, as the CSF/plasma ratios for leptin and adiponectin are also decreased." (PMID 28515688, 2017). "In aggregate, these findings suggest that inhibiting S-nitrosation of insulin signaling pathway may be a valuable ally in treating obesity and its related diseases." (PMID 28835706, 2017). "Also, the obese group showed a strong tendency of decreased Akt phosphorylation (by 61%, t = 2.137, df = 10, p = 0.0584) in relation to the control group, which demonstrates the insulin signaling pathway impairment in response to obesity induction." (PMID 29062272, 2017). "The rate of insulin transport across the BBB is also slowed by obesity and aging." (PMID 28515688, 2017). "In addition, PIKE is involved in obesity development since it plays a role in insulin-suppressed AMPK activation." (PMID 28170448, 2017). "Improved metabolic function (insulin sensitivity) and Anti-obesity." (PMID 29167659, 2017). "Thus, genetic or pharmacological inhibition of Drp1 improved muscle insulin sensitivity and insulin signaling in obese mice, as well as conferred protection against high-fat diet-induced obesity in liver-specific Drp1 deleted mice." (PMID 29257072, 2017). "Differences in FFA metabolism between obesity and normal weight subjects might partial explain why we only found the stronger correlation of calf circumference with insulin resistance among subjects who BMI ≥24 kg/m2." (PMID 28558676, 2017). "Additionally, high fat diet-induced obesity galvanizes the transition of type I muscle fibers to type II, which are less responsive to insulin." (PMID 29108358, 2017). "In fact, IL-6 and IL-1β are positive modulators of insulin resistance in adipose tissue and the heart during obesity, which might be of medical interest." (PMID 29201273, 2017). "Obesity leads to HL that further exacerbates the HI via the reduction of hepatic insulin clearance." (PMID 28466412, 2017). "Here by inducing expression of constitutively active Smoothened (SmoM2) or Gli2 (ΔNGli2) in the adipocyte lineage of postnatal mice, we show that targeted activation of Hh signaling suppresses high-fat-diet-induced obesity and improves whole-body glucose tolerance and insulin sensitivity." (PMID 29205155, 2017). "In adipocytes, PPAR-γ is known for its anti-obesity capability and insulin sensitization." (PMID 28804438, 2017). "Thus, exercise-trained Atg7h&mKO mice are better protected against diet-induced obesity and insulin resistance when compared to exercise-trained control mice." (PMID 28801668, 2017). "Differences in insulin could also account for obesity-related differences in the effects of O3 on lung BCAA metabolism." (PMID 28704544, 2017). "Furthermore, several compounds and natural products with anti-angiogenic properties exert anti-obesity and insulin sensitizing effects." (PMID 28355132, 2017). "These properties of insulin and IGF1 could underlie increased growth of breast cancer in obesity and of osteosarcoma in puberty." (PMID 28316059, 2017). "However when PA was given to rats with diet-induced obesity, an improvement was observed in plasma glucose and insulin levels and glucose-normalizing capacity over a glucose tolerance test." (PMID 28558700, 2017). "Dynamic changes in DNA methylation might be an early event that drives the transcription of genes involved in the orchestral regulation of insulin sensitivity in human obesity." (PMID 28250848, 2017). "Our findings expand the possibilities for new potential therapeutic strategies, focused on insulin degradation, that could be used in the treatment and/or prevention of diseases related to hyperinsulinemia, such as obesity and T2DM." (PMID 28429777, 2017). "Additionally, it was noticed that PSO consumption improves glucose and insulin sensitivity and fat diet-induced obesity in mice." (PMID 28558700, 2017).
Obesity (continued). "Differences in insulin could also account for obesity-related differences in the effects of O3 on BCAA metabolism." (PMID 28704544, 2017). "Taken together, T2 might contribute to improvement of insulin sensitivity and resultant lowering of the elevated blood glucose level in obesity in spite of its reduction of sulfur-containing components." (PMID 28400840, 2017). "It is activated by insulin concentration, which is often elevated in individuals with obesity." (PMID 28095459, 2017). "It is shown that injection of αGalCer in obesity increases the iNKT cell amount and induces weight loss rapidly, anti-inflammatory macrophage differentiation, and reversal of glucose and insulin sensitivity without hypoglycemia." (PMID 28251163, 2017). "Several studies have shown that a high fat diet with butyrate supplementation could alleviate obesity and improve insulin sensitivity in skeletal muscle of mice." (PMID 28055958, 2017). "Moreover, the gut microbiota have significant roles to play in HFD-induced obesity in terms of energy harvest, insulin resistance, and modulations to host metabolisms." (PMID 28520815, 2017). "We hypothesised that it may be the altered levels of insulin in the milk that contributed to attenuation of early-overfeeding induced obesity in their rat offspring." (PMID 28794439, 2017). "In addition, risk factors shared between DMII, CAD and CHF include physical inactivity, obesity and central obesity, hypertension, and raised concentrations of insulin, HbA1c, triglycerides and fasting plasma glucose." (PMID 28854280, 2017). "Therefore, our findings revealed a novel role for NOS in the control of food intake, showing that iNOS-induced S-nitrosation of insulin signaling pathway induces chronic changes in energy homeostasis, which promotes obesity." (PMID 28835706, 2017). "Metabolic hormones such as insulin, the levels of which are significantly increased with obesity, may also contribute to the sex specific response of the autonomic nervous system to obesity, notably play a role in the decreased vagal tone." (PMID 28184201, 2017). "In peripheral organs, ceramides are important mediators of lipotoxicity: they accumulate in insulin-sensitive tissues and in pancreatic β cells during the development of obesity, and their intracellular levels correlate with both insulin resistance and β cell apoptosis." (PMID 29075199, 2017). "More importantly, we showed that combination of BG with MLE, another popular dietary component, that is gaining increasing attention in the field of obesity management, has synergetic benefits especially on insulin sensitivity and liver oxidative stress management." (PMID 29023387, 2017). "For instance, GPR43-deficient (Gpr43-/-) mice develop obesity when they are on high fat and normal chow diets, and GPR43 activation increases energy expenditure and preferentially enables fat consumption via inhibition of insulin signaling in the WAT." (PMID 28692672, 2017). "Moreover, in a diet-induced obese mouse model, macrophage polarization can be regulated for influencing obesity-induced adipose tissue inflammation or insulin resistance." (PMID 28466023, 2017). "Sympathetic over-activity is in connection with obesity, reduced insulin sensitivity, inflammation and the metabolic syndrome, all of which could increase the risk of T2DM." (PMID 28572617, 2017). "However, there is no study investigating the relationship between the GMV of the region related to obesity and plasma insulin." (PMID 28197123, 2017). "Indeed, deletion of S6K1 protects against diet-induced obesity, enhances insulin sensitivity and increases lifespan in mice." (PMID 28795262, 2017). "Both models of obesity display increases in insulin positive area over lean control mice." (PMID 29038790, 2017).
Obesity (continued). "Our data confirm the important role of TUDCA in the regulation of insulin signaling and secretion, and further elucidates the function of this bile acid on insulin metabolism and its importance in pathological conditions such as obesity and T2D." (PMID 29093479, 2017). "Further testing for isoform specificity, using p110α and p110δ discriminating compounds, revealed that the anti-obesity effect was particularly prominent upon inhibition of p110α, the principal insulin activated isoform, although inhibition of p110δ did contribute to the overall effect." (PMID 28795262, 2017). "Targeting actions toward insulin-related metabolic processes could also lead to more homogeneous evidence to tackle obesity and overweight." (PMID 28485680, 2017). "The HFD alone induced obesity-associated with hepatic steatosis, hyperleptinemia, and only transient increases in HOMA-IR values, C-peptide levels, hypertriglyceridemia, and reduced glucose-to-insulin ratio." (PMID 28134848, 2017). "In addition, insulin and leptin levels were significantly affected by obesity and exercise training (Ob > C and Ob > ObET, respectively, P < 0.05)." (PMID 29038363, 2017). "Recently, another component of the Mediterranean diet, resveratrol, has been shown to modulate positively gut microbiota enhancing glucose tolerance in a mice model of obesity and also through a duodenal Sirt-1 pathway into the hypothalamus enhancing hypothalamic insulin-resistance." (PMID 28335507, 2017). "First, obesity decreases metabolic function (e.g., impairs insulin signaling, decreases mitochondrial efficiency), increases glutocorticoid and inflammatory signaling, and decreases structural and functional integrity of brain circuits (most consistently in medial temporal and frontal lobes)." (PMID 28507516, 2017). "Taken together, these data indicate that EETs reduce chemokine expression that could mediate obesity-induced macrophage recruitment and activation in adipose tissue, and thus preserve the insulin sensitivity in adipocytes." (PMID 28440284, 2017). "LCN2 regulates lipid and energy metabolism in obesity and is upregulated in response to insulin." (PMID 29234288, 2017). "Obesity, which is a state of chronic low-grade inflammation and a risk factor for IR and NAFLD, is induced by over-nutrition and is a primary cause of decreased insulin sensitivity." (PMID 29037210, 2017). "Hyperphagia and elevated levels of both insulin and leptin are common features of obesity." (PMID 28360931, 2017). "However, we unexpectedly discovered that p32 heterozygous mice, though developmentally normal, display robust resistance to both age- and high-fat diet-induced obesity and maintain insulin sensitivity well into late adulthood." (PMID 28720899, 2017). "Moreover, our results demonstrate, for the first time, that the PG becomes severely insulin resistant under diet‐induced obesity in mice." (PMID 28244645, 2017). "While solid evidence exists that obesity-associated IR affects at least parts of the DMN4, the current study showed for the first time that DMN functional connectivity plays a pivotal role in central insulin action in cognitively healthy young adults." (PMID 28487570, 2017). "Infusion of isolated macrophages from Lactobacillus-infused mice could impede the HFD-mediated obesity and reduced sensitivity to insulin and glucoses." (PMID 28928739, 2017). "In addition to baseline liver fat, several measures of obesity and concentrations of fasting glucose, insulin, triglycerides and HDL cholesterol predicted liver fat measured by 1H-MRS at follow-up in univariate analyses." (PMID 29109528, 2017). "For example, Rb1 has a great potential for exerting anti-obesity effects by stimulating c-Fos expression in brain areas involved in energy homeostasis; Rb1 also promotes glucose homeostasis by increasing insulin sensitivity." (PMID 29114222, 2017).
Obesity (continued). "Our previous in vivo research found that both male and female mutant mice, whose Stat5a/b loci in the CNS were deleted (Stat5NKO), developed severe obesity, accompanied by hyperphagia, hyperleptinemia, impaired thermal response to the cold, and insulin resistance." (PMID 28806763, 2017). "The beneficial effects of Ilex latifolia Thunb on the development of obesity prompted us to investigate whether insulin sensitivity and glucose homeostasis of mice were affected by Ilex latifolia Thunb supplementation." (PMID 29116160, 2017). "Moreover, we show that obesity promotes S-nitrosation of insulin signaling pathways while inhibition of iNOS restores hypothalamic insulin signaling." (PMID 28835706, 2017). "The insulin signaling network is influenced by obesity and may interact with the estrogen receptor α (ERα) signaling." (PMID 29234306, 2017). "Thus far, studies of skeletal muscle have predominantly focused on defects in orchestrating insulin signals during obesity." (PMID 27619557, 2017). "DNA methylation of the Pgc-1α promoter decreases skeletal muscle Pgc-1α expression and mitochondrial number and function, both of which may be important in determining insulin sensitivity during obesity." (PMID 28191013, 2017). "In conclusion, the reduction in HFD-induced obesity after BMT in mice is at least partly due to alterations in the adipose tissue cell pool composition as well as to a decreased pancreatic secretion of the anabolic hormone insulin." (PMID 28445487, 2017). "Key metabolic hormones, such as insulin, leptin, and adiponectin, have been studied extensively in obesity, however the pathophysiologic relevance of the calcitonin family of peptides remains unclear." (PMID 28666011, 2017). "This means that obesity itself may regulate not only insulin sensitivity, but also the serum FGF21 levels." (PMID 28582462, 2017). "Finally, the present study, suggests that the impact of impairments in insulin signaling in obese populations cannot be discounted, and future studies of the influence of obesity on brain-behavior relationships should control for IR." (PMID 29228027, 2017). "In obesity, the greater portion of the adipose tissue comprises fat, and there is increased pro-inflammatory cytokine secretion, macrophage infiltration, and reduced insulin sensitivity." (PMID 29021781, 2017). "Considering all these points previously discussed, it would be legitimate to hypothesize that ANGPTL4 transcription regulation by PPARs constitutes a gateway between obesity, insulin sensitivity, and cancer." (PMID 28182091, 2017). "High-fat diets enriched in saturated fat may promote an increase in body weight and lead to obesity, liver injury, hepatic insulin resistance, and steatosis." (PMID 28356106, 2017). "Moreover we have shown at 8 weeks of age that offspring of obese dams when weaned onto chow are insulin resistant so this phenotype also develops independently of offspring obesity." (PMID 28338072, 2017). "In contrast, the “accelerator hypothesis” and the “overload hypothesis” suggest that obesity contributes to insulin resistance and increased insulin demand." (PMID 28763444, 2017). "Therefore, increasing MANF level in the hypothalamus leads to an impaired insulin response, which results in hyperphagia and obesity." (PMID 28924165, 2017). "This occurred in nonobese people with more deficient endogenous insulin secretion, not in those with insulin still secreted in large quantities, as in obesity." (PMID 28151905, 2017). "Conversely, patients with common obesity show high-circulating leptin and insulin levels." (PMID 28626772, 2017). "Given that the balance shifting between M1- and M2-like macrophages is critical for the progression of inflammatory responses in obese adipose tissue, it is plausible that macrophage VLDLR elevation in obesity confers systemic insulin resistance through adipose tissue inflammation." (PMID 29057873, 2017).
Obesity (continued). "Therefore, taking our results together, the MKP-3 increased in the hypothalamus, at least in part, contributing to the insulin signaling pathway impairment due to its effect on FoxO1 and Erk dephosphorylation, which induce hyperphagia and obesity in animals." (PMID 29062272, 2017). "Our results would support a direct role for obesity and the insulin pathway in pancreatic cancer." (PMID 28954281, 2017). "Given the interplay between obesity, insulin/glucose signaling and OC, we hypothesized that obesity creates a unique environment contributing to the generation of tumors that are metabolically distinct from those developing in a “lean” host milieu." (PMID 29340030, 2017). "However, currently, various studies conducted in this population have indicated an increase in the incidence of obesity and resistance to insulin related to treatment in ALL and lymphoma survivors during therapy." (PMID 28193268, 2017). "In obesity fasting levels of both glucagon and insulin are elevated." (PMID 28680093, 2017). "Similarly, the abnormal production of leptin in obesity leads to leptin resistance and supresses insulin-stimulated glucose metabolism." (PMID 29021781, 2017). "In conclusion, the altered structure and function of the putamen could play important roles in obesity and aberrant insulin." (PMID 28197123, 2017). "HRs and 95% CIs were calculated using Cox proportional hazards models, adjusted for confounding factors; in another model, they were additionally adjusted for potential mediators, including obesity, C-reactive protein, glucose and insulin, as well as for levels of total oestradiol and androgens." (PMID 28721436, 2017). "Serum insulin levels strongly correlated with both total body mass and fat mass in both diet-induced and genetic mouse models of obesity." (PMID 29038790, 2017). "There is an established connection between obesity and the insulin signaling pathway." (PMID 29234306, 2017). "For example, a molecular mechanism of tumorigenesis in obesity has been proposed, involving secretion of adipokines (leptin, adiponectin and increased inflammatory cytokines) and secondary effects of obesity that increase anabolic pathways, such as insulin-insulin growth factor (IGF) signaling." (PMID 28580187, 2017). "(2016) found miR155 deficiency in female mice to be effective at preventing diet‐induced obesity as characterized by decreased body weight gain, increased expression of adipogenic genes, blunting of adipose tissue inflammation, and improved insulin sensitivity." (PMID 28947593, 2017). "Nonetheless, Treg depletion experiments have demonstrated their significance in limiting the development of the obese phenotype, wherein rodent models of genetic and HFD-induced obesity exhibited increased AT inflammation and decreased systemic insulin sensitivity." (PMID 29186929, 2017). "However, in isolated human atrial myocytes, insulin, which is generally elevated in obesity and metabolic syndrome, has been shown to increase ICa, L and slow its inactivation, which would be in line with prolongation of APD." (PMID 28680407, 2017). "Our study revealed that fed late adult mice concurrently with starting obesity demonstrated impaired glucose metabolism including increased plasma insulin levels, decreased glucose tolerance compared to younger mice, and decreased expression of Slc2a4 gene in WAT (compared to early adult mice)." (PMID 29038358, 2017). "It would be interesting to investigate whether Wnt3a-induced insulin production from the specific neurons in the hypothalamus can regulate the food intake and protect from obesity." (PMID 26956881, 2016). "Moreover, mice lacking PAI-1 have increased energy expenditure, improved glucose tolerance, enhanced insulin sensitivity, and are resistant to diet- or genetically induced obesity." (PMID 27187453, 2016).